LOX (lysyl oxidase)
Diseases named in the same sentence as LOX in open-access papers (continued):
Sharing a sentence is not in itself a finding about the gene and the disease.
breast carcinoma (continued). "TNBCs display higher LOX expression, and reports in the literature suggest that LOX can be used as a prognostic marker for breast cancer." (PMID 26265048, 2015). "Later, BAPN was proposed to also be useful in the treatment of cancers with LOX hyperexpression, such as melanoma, head and neck carcinoma and breast carcinoma." (PMID 25790191, 2015). "It has been reported that hypoxia-induced expression of HIF-1α leads to the release of LOX, an enzyme that crosslinks extracellular matrix proteins such as collagen and promotes breast cancer metastasis." (PMID 25238333, 2014). "Conversely, the LOX pro-peptide (LOX-PP), which is released during the maturation of the pro-LOX enzyme, reduces breast cancer cell motility by attenuating phosphorylation and activation of p130Cas/BCAR1." (PMID 25606587, 2014). "Several lines of evidence suggest a functional link of LOX with the estrogen receptor (ER) in breast cancer." (PMID 25141126, 2014). "For example, the enzyme lysyl oxidase (LOX) confers a motile phenotype on breast cancer cells by facilitating the formation of a p130Cas/Crk/DOCK180 complex, which sustains Rac activity and subsequent actin polymerization." (PMID 25606587, 2014). "A coding SNP in the LOX gene (rs1800449; c.473G>A; Arg158Gln; R158Q; hereafter referred to as G473A) was genotyped in a hospital-based case-control study of 386 breast cancer patients and 243 female controls." (PMID 25141126, 2014). "LOX elevation occurs in metastatic and/or invasive breast cancer cell lines, and hypoxic primary tumor cells increase LOX expression and secretion, enabling cell movement to more oxygenated and thus more nutrient-rich areas." (PMID 25238333, 2014). "Presence of the Gln-variant, which is encoded by the minor A-allele, was found to profoundly impair the tumour suppressive activity of the LOX-PP in a xenograft model of NF639 breast cancer cells." (PMID 25141126, 2014). "Clinical studies have shown that both HIF-1α and LOX are overexpressed in breast cancer patients, and this overexpression increases with disease progression, resulting in a high mortality rate." (PMID 25238333, 2014). "That LOX was expressed in 79% of human breast cancers revealed the attenuated metastasis of human breast cancer cells by a downregulation of adhesion kinase and the paxillin-signaling pathway." (PMID 24885752, 2014). "LOX overexpression is found in myofibroblasts and myoepithelial cells around in situ tumors and at the invasion front of infiltrating breast cancers." (PMID 24885752, 2014). "LOX overexpression can be found in myofibroblasts and myoepithelial cells around in situ tumors and at the invasion front of infiltrating breast cancers." (PMID 24885752, 2014). "Direct interaction of LOX-PP with CIN85 was confirmed using co-immunoprecipitation analysis of lysates from breast cancer cells and of purified expressed proteins." (PMID 24167568, 2013). "The LOX-PP interaction with CIN85 was shown to reduce the invasive phenotype of breast cancer cells, including their ability to degrade the surrounding extracellular matrix and for Matrigel outgrowth." (PMID 24167568, 2013). "A profound decrease in collagen invasion by breast cancer cells was noted with LOX-PP-WT compared to the control EV cells." (PMID 24167568, 2013). "The interaction with LOX-PP competed for CIN85 association with c-Cbl and profoundly reduced the invasive phenotype of breast cancer cells, identifying a new mechanism to inhibit invasion." (PMID 24167568, 2013). "LOX-PP inhibited the Her-2/Ras signaling axis in breast cancer cells, and reduced the Her-2-driven breast tumor burden in a xenograft model." (PMID 24167568, 2013). "Recent studies revealed that HIF-1α-induced LOX overexpression promoted the metastasis of breast cancers in a mouse model and was correlated with poor prognosis of ER negative patients." (PMID 23496980, 2013).
breast carcinoma (continued). "Bone marrow-derived human MSCs promote de novo production of lysyl oxidase (LOX) from human breast carcinoma cells, which is sufficient to enhance the metastasis of otherwise weakly metastatic cancer cells to the lungs and bones." (PMID 26237148, 2013). "In a mouse model of breast cancer, inhibition of LOX reduced cancer cell motility and invasiveness and prevented metastasis." (PMID 22509805, 2012). "LOX was previously known to cross-link collagens and elastins in the ECM but had also been associated with increased breast cancer cell invasion in vitro." (PMID 22509805, 2012). "Subsequently, LOX-PP was shown to reduce the migratory phenotype of mouse breast cancer cells driven by Her-2/Neu, which signals via Ras and their ability to form tumors in a nude mouse xenograft model." (PMID 22438909, 2012). "LOX-PP also attenuated fibronectin-mediated activation of focal adhesion kinase in breast cancer cells, and fibroblast growth factor (FGF)-2-induced proliferation of prostate cancer cells." (PMID 22438909, 2012). "The region of LOX-PP encompassing aa 26 to 100 is necessary for its interaction with c-Raf in breast cancer cells." (PMID 22438909, 2012). "Conversely, the 18-kDa LOX propeptide was found to be an effective inhibitor of the more invasive phenotype of breast cancer cells driven by ERBB2 and has been suggested to improve treatment in this subtype of breast cancer." (PMID 21731642, 2011). "Lysyl oxidase (Loxl1), a matrix remodeling protein, is known to play a role in breast cancer migration, adhesion, and metastasis." (PMID 21589862, 2011). "With this background, we studied the ability of β-aminopropionitrile (BAPN), an irreversible inhibitor of LOX, to regulate the metastatic colonization potential of the human breast cancer cell line, MDA-MB-231." (PMID 19440335, 2009). "Our findings suggest that LOX likely plays an important role in regulating extravasation and/or tissue colonization by circulating breast cancer cells." (PMID 19440335, 2009). "During bone tissue colonization, breast cancer cells secrete lysyl oxidase (LOX) and connective tissue growth factor (CTGF), which induce extracellular matrix sclerosis and angiogenesis, thereby facilitating tumor cell proliferation and metastatic establishment." (PMID 40630133, 2025). "LOX plays a critical role in the metastasis of breast cancer cells and the prognosis of patients." (PMID 39247609, 2024). "Furthermore, macrophages drive stromal cell-dependent collagen crosslinking and stiffening promoting breast cancer aggression due to the high expression of LOX." (PMID 38246995, 2024). "LOX may also serve as an independent predictor of prognosis in breast cancer patients, highlighting its potential utility in the diagnosis and management of breast cancer." (PMID 39247609, 2024). "The involvement of the LOX protein in breast cancer has been extensively studied." (PMID 39247609, 2024). "Thus, mature LOX promoted a migratory phenotype through changes in actin filament polymerization in breast cancer cell lines." (PMID 39247609, 2024). "Hypoxic tumors, along with HIF1 activation (e.g., breast cancer and head and neck cancer) are the main source of LOX, which is released systemically and disrupts ECM homeostasis in the pre-metastatic lung or bone by crosslinking ECM molecules and primarily collagen." (PMID 37350937, 2023). "Not only are LOX enzymes upregulated in MSCs of breast cancer patients, but MSCs are enriched in breast tissue and in circulation, suggesting that LOX expressing MSCs locally drive EMT and begin to promote the formation of cancer-permissive ECM in distal tissue sites." (PMID 38002286, 2023). "Thymidine kinase-1 (TK1), lysyl oxidase (LOX), lysine demethylase 5B (KDM5B), proteasome 26S subunit non-ATPase 4 (PSMD4), and nuclear factor erythroid 2-like 3 (NFE2L3) genes are implicated in relapse and poor prognosis of patients with breast cancer." (PMID 37767092, 2023).
breast carcinoma (continued). "TGF-β and TNF-α, pro-inflammatory cytokines that are extensively expressed in the tumor microenvironment, upregulate the LOX expression via the reactive oxygen species–activated NF-κB/extracellular signal-related kinase pathway, thus promoting the progression of breast cancer metastasis." (PMID 35138531, 2023). "Moreover, high expression of collagens I–V, LOX and LOXL1-2 in cancers, including breast carcinoma, is associated with therapy resistance." (PMID 35267548, 2022). "Unlike the native protein, abnormal LOX due to rs1800449 point mutation failed to inhibit the invasiveness of NF639 breast cancer cells." (PMID 36292250, 2022). "We therefore screened MDA-MB-231 breast cancer cells in which we knocked out all five lysyl-oxidase genes (5× cells) for the genes whose expression was either inhibited or enhanced and then further selected genes whose expression was rescued following the expression of the full-length LOX cDNA." (PMID 36232621, 2022). "Moreover, studies have shown that LOX participates in the migration and tissue colonization of circulating breast cancer cells." (PMID 36293126, 2022). "Recently, more and more experiments have demonstrated that LOX mRNA and protein expression are significantly upregulated in various types of cancer, such as breast cancer, lung cancer, gastric cancer, and liver cancer; the high expression can promote tumor invasion and metastasis." (PMID 36293126, 2022). "In sum, hypoxia directly regulates ECM composition via multiple enzymes and, as such, P4HA1, P4HA2, PLOD2, and LOX enzymes could be used as biomarkers in breast cancer progression." (PMID 36140753, 2022). "However, LOX silencing in breast cancer cells by siRNA can downregulate the expression of matrix metalloproteinase 2 (MMP-2) and MMP-9 in breast cancer tissues." (PMID 36293126, 2022). "Taken together, these results illustrate that the role of catalytically active LOX in breast cancer metastasis is multifaceted and may depend on the specific cell type from which the enzyme is derived." (PMID 35804902, 2022). "Administration of βAPN to tumor-bearing PyMTmgko mice attenuated pulmonary metastatic burden and reduced the number of viable tumor cells in the systemic circulation, suggesting that LOX facilitates breast cancer metastasis by promoting cancer cell intravasation into the vasculature." (PMID 35804902, 2022). "We will therefore concentrate our future efforts on the elucidation of the mechanism by which LOX induces expression of the STOX2 gene and on the elucidation of the role of STOX2 in the biological responses to LOX expression in breast cancer cells and normal cells." (PMID 36232621, 2022). "In addition, it was observed that enhanced expression of LOX in breast cancer cells activates the secreted protease HTRA1, which inhibits TGF-β1 signaling." (PMID 35682926, 2022). "Thus, providing a basis to clarify the potential usefulness of each LOX as progression biomarker or therapeutic target in breast cancer." (PMID 35800439, 2022). "Hence, LOX inhibition is now considered an effective therapeutic approach for breast cancer treatment." (PMID 34981672, 2022). "However, no studies have been performed to develop a lipid vesicle targeting LOX, combined with chemotherapy-delivery to evaluate its efficacy compared to standard clinical treatment available for breast cancer patients (e.g., epirubicin)." (PMID 33658580, 2021). "Finally, we searched the TCGA invasive breast carcinoma data set for the survival of breast cancer patients relative to LOX expression level." (PMID 34617419, 2021). "Additionally, LOX expression has been linked to MAPK signaling through p38-MAPK, ERK and JNK pathways in cardiac fibroblasts and breast cancer models." (PMID 33513979, 2021). "Likewise, macroH2A1.2 was shown to cooperate with EZH2 to establish and maintain a repressive chromatin mark at the locus of the breast cancer-induced osteoclastogenic factor lysyl oxidase (LOX)." (PMID 34203934, 2021).
breast carcinoma (continued). "Interestingly, a transplantable breast cancer model shows that secreted LOX regulates bone homeostasis via osteoclastogenesis." (PMID 33123472, 2020). "A model for breast cancer liver metastasis was established involving diverse factors from breast tumor cells and the liver microenvironment such as integrin complexes, HIFs and LOX." (PMID 33489906, 2020). "In addition, clinical studies have shown that both HIF-1α and LOX are overexpressed in breast cancer patients, and this overexpression increases with disease progression and is associated with a high mortality rate." (PMID 33126606, 2020). "We have previously reported elevated expression of LOX with incidence of mammary tumors in bitches." (PMID 32542505, 2020). "For instance, it has been demonstrated that, by functionalizing the surface of nanoparticles, with LOX inhibiting antibodies, it is possible to suppress mammary cancer cell growth and invasion more effectively than soluble anti-LOX antibodies both in vitro and in vivo." (PMID 32604738, 2020). "Also, over expression of LOX is considered tumor marker for invasiveness in breast cancer, head and neck squamous cell, prostatic and renal cell carcinomas." (PMID 32542505, 2020). "We thus hypothesized that LOX is involved in the progression of primary breast tumors, and analyzed the prognostic significance of its expression in a cohort of 41 human breast cancer patients." (PMID 31439905, 2019). "However, much less is known about the effects of hypoxia induced LOX on breast cancer lung metastases." (PMID 30181809, 2018). "Besides MMPs and LOX, other ECM modifying enzymes, such as urokinase plasminogen activator (uPA) system and cathepsins, are also associated with breast cancer and metastatic progression." (PMID 30237810, 2018). "Next, we showed hypoxia enhanced breast cancer cell migration, and expression and secretion of lysyl oxidase (LOX), which is copper-dependent amine oxidase and has the primary function to drive the crosslinking of collagen and elastin and is regulated by hypoxia." (PMID 30181809, 2018). "In addition to the decrease of mammary tumor growth, LOX inhibition has also been reported to reduce cancer cell motility, reverse hypoxia-induced EMT and suppress metastasis." (PMID 29458390, 2018). "In the same study, endogenous LOX mRNA expression could be induced in poorly invasive breast cancer cell lines by cultivating cells in the presence of fibroblasts-conditioned medium or matrix, suggesting a role for stromal fibroblast in LOX regulation." (PMID 28743863, 2017). "Therefore, the expression of LOX can be expected to be high in aggressive breast cancers with a high histological grade and high Ki-67 LI." (PMID 29261141, 2017). "Additionally, a breast cancer model system has shown that fibroblasts over-expressing LOX increase tumor cell invasiveness in vivo, by increasing matrix stiffening and focal adhesion formation." (PMID 26716418, 2016). "Given that survival us usually poor among patients with high LOX expression, LOX could be a useful biomarker to stratify patients with ER– breast cancer and direct personalized therapies." (PMID 27147578, 2016). "The authors of that report suggest administration of bisphosphonate to breast cancer patients with LOX overexpression may prevent establishment and proliferation of CTCs within bone." (PMID 27147578, 2016). "Since LOX expression positively correlates with cisplatin and gemcitabine sensitivity, LOX+ ER– breast cancer patients may show a higher response rate to these drugs." (PMID 27147578, 2016). "Moreover, HIF‐1α upregulates lysyl‐oxidase (LOX) which, in breast cancers, controls migration and invasion." (PMID 27138568, 2016). "TNF-α, a pro-inflammatory cytokine, induces LOX expression via the reactive oxygen species-activated NF-κB/extracellular signal-related kinase pathway, thus promoting the progression of cardiac fibrosis and breast cancer metastasis." (PMID 28036074, 2016).
breast carcinoma (continued). "Furthermore, the results of gene set enrichment analysis (GSEA) indicate that LOX expression correlates positively with gene sets that represent cancer cell migration and metastasis in breast cancer (P < 0.0001)." (PMID 27147578, 2016). "Bisphosphonate treatment may suppress bone metastasis in ER– breast cancer patients overexpressing LOX." (PMID 27147578, 2016). "Therefore, we examined expression of ELK3, GATA3, and LOX by constructing a heat map matrix using public microarray data derived from breast cancer cell lines." (PMID 27556500, 2016). "Although we suggest several therapeutic interventions that may help in the management of LOX+ ER– breast cancer patients, experiments to validate the function of LOX in ER– breast cancer are still needed." (PMID 27147578, 2016). "Hyaluronan was recently suggested to work as an inducer of LOX expression in breast cancer cells, which may explain the positive correlation to LOX IR in tumor epithelial cells." (PMID 26501565, 2015). "High LOX expression is related to a poor breast cancer patient outcome." (PMID 26265048, 2015). "A conclusion highlighted by Cox and colleagues is that LOX expression in ER– breast cancer could be a useful biomarker for increased bone metastasis risk as well as for the identification of patients for bisphosphonate treatment in the adjuvant setting." (PMID 26337273, 2015). "Moreover, another inhibitor of LOX, magnolol, presented a similar effect in a breast cancer model in vitro." (PMID 25790191, 2015). "Hypoxic breast cancer cells produce elevated levels of LOX, which may play a critical role in tumor progression and metastasis." (PMID 26265048, 2015). "Expression of LOX is elevated in many human cancers, including breast cancer." (PMID 26265048, 2015). "Another mechanism by which MSCs may increase tumorigenesis of breast cancer cells is the induction of lysyl oxidase which was shown to enhance the metastatic potential of breast cancer cells in xenografts." (PMID 26273308, 2015). "The role of specific targeting of LOX using molecular imaging techniques may be used for breast cancer staging and monitoring responses to therapy." (PMID 26265048, 2015). "Although direct mechanisms have not been elucidated, MMPs are associated with LOX expression in breast cancer." (PMID 24338768, 2014). "High LOX expression was associated with a significantly shorter metastasis-free and overall survival in breast cancer patients with estrogen receptor (ER) negative, but not ER positive tumours, as well as in head and neck cancer patients." (PMID 25141126, 2014). "LOX activity was reported to be greater in human breast cancer than in normal tissues, a finding that suggests that LOX plays a key role in creating the cellular microenvironment necessary for a pre-cancerous niche (PCN), one of the prerequisites for the induction of cancer." (PMID 24885752, 2014). "Furthermore, inhibition of LOX activity eliminated tumor dissemination in an orthotopic mammary tumor model." (PMID 25052686, 2014). "The lysyl oxidase gene inhibits Ras signaling in transformed fibroblasts and breast cancer cells." (PMID 24167568, 2013). "Thus, interaction of the atypical ligand of LOX-PP with CIN85 mediates the ability of this tumor suppressor to reduce invasive phenotype of breast cancer cells." (PMID 24167568, 2013). "The role of LOX in tumor progression has been most extensively studied in breast cancer." (PMID 23425977, 2013). "Thus, LOX-PP interacts with CIN85 via a novel SH3-binding motif and this association reduces CIN85-promoted invasion by breast cancer cells." (PMID 24167568, 2013).